SLC35A2 (solute carrier family 35 member A2)
Diseases named in the same sentence as SLC35A2 in open-access papers (continued):
Sharing a sentence is not in itself a finding about the gene and the disease.
Intellectual disability (3 papers, 2021 to 2025). "A literature review identified four male cases with hemizygous variants in SLC35A2, and their clinical features included short stature, abnormal liver function, language delay, intellectual disability, mild facial abnormalities, skeletal deformities and epileptic seizures." (PMID 41437099, 2025). "Patients with SLC35A2-CDG have seizure spasms and arrhythmias as their main manifestations, along with severe intellectual disability and some systemic manifestations." (PMID 36419532, 2022).
Cerebral atrophy (2 papers, 2018 to 2019). Atrophy (wasting, decrease in size of cells or tissue) affecting the cerebrum. "In eight patients with SLC35A2-CDG in the literature, manifestations include seizures, failure to thrive, delayed myelination and cerebral atrophy." (PMID 29907092, 2018).
colon adenocarcinoma (2 papers, 2023 to 2025). "One bioinformatic analysis exhibited high expression of SLC35A2 in many cancer types including colon adenocarcinoma, and overexpression of SLC35A2 is related to decreased lymphocyte infiltration." (PMID 40303483, 2025). "Our study revealed that SLC35A2 is upregulated in 20 types of cancer, including lung adenocarcinoma (LUAD), breast invasive carcinoma (BRCA), colon adenocarcinoma (COAD), and lung squamous cell carcinoma (LUSC)." (PMID 37275857, 2023).
influenza (2 papers, 2024 to 2025). An acute viral infection of the respiratory tract, occurring in isolated cases, in epidemics, or in pandemics; it is caused by serologically different strains of viruses (influenzaviruses) designated A, B, and C, has a 3-day incubation period, and usually lasts for 3 to 10 days. "As we have confirmed that SLC35A2 affects paramyxovirus virus-cell and cell-to-cell fusion, there is a possibility that this gene also affects fusion processes in infections with influenza and other viruses." (PMID 39792924, 2025). "As we have confirmed that SLC35A2 affects paramyxovirus virus-cell and cell-to-cell fusion, there is a possibility that this protein also affects fusion processes in infections with influenza and other viruses." (PMID 39253522, 2024).
Lennox-Gastaut syndrome (2 papers, 2022 to 2025). Lennox-Gastaut syndrome (LGS) belongs to the group of severe childhood epileptic encephalopathies. "Patients harboring the SLC35A2 variants were more likely to present as Lennox-Gastaut syndrome, when compared with those who were SLC35A2-negative." (PMID 39902276, 2025).
lymph node metastasis (2 papers, 2023 to 2025). "Another research revealed that upregulation of SLC35A2 is positively correlated with lymph node metastasis and clinicopathological staging." (PMID 40303483, 2025). "The expression of SLC35A2 was analyzed according to lymph node metastasis status, and it was found that there was a difference between N0 and N1 stages (p < 0.05)." (PMID 37889544, 2023).
melanoma (2 papers, 2007 to 2022). A malignant, usually aggressive tumor composed of atypical, neoplastic melanocytes. "Notice that the expression of Slc35a2, an UDP-galactose transporter, was also upregulated by 3.8 folds in melanoma cells." (PMID 17594473, 2007).
pancreatic adenocarcinoma (2 papers, 2021 to 2023). "CNV and SLC35A2 expression were negatively correlated in five cancers, such as pancreatic adenocarcinoma (PAAD) (considered significant when FDR ≤ 0.05), suggesting that SLC35A2 expression was primarily regulated by other factors such as the activation of transcription in these cancers." (PMID 37275857, 2023).
stomach adenocarcinoma (2 papers, 2023). "Herein, a system analysis was conducted to evaluate the role of SLC35A2 in prognostic, and immunology in stomach adenocarcinoma (STAD)." (PMID 37467193, 2023). "Furthermore, the SLC35A2 promoter region was hypomethylated in testicular germ cell tumors (TGCT), BLCA, BRCA, esophageal carcinoma (ESCA), LIHC, prostate adenocarcinoma (PRAD), and stomach adenocarcinoma (STAD)." (PMID 37275857, 2023).
virus infection (2 papers, 2024 to 2025). "We next focused on investigating where SLC35A2 played a critical role during the virus infection cycle." (PMID 39253522, 2024). "Instead, SLC35A2 is crucial for the fusion of SeV with the cells and for MuV induced cell-to-cell fusion and syncytia formation suggesting a specific role for this protein in fusion events during virus infection." (PMID 39253522, 2024). "However, SLC35A2 is crucial for the fusion of SeV with the target cell and for MuV induced cell-to-cell fusion and syncytia formation, suggesting a specific role for this protein in fusion events during virus infection." (PMID 39792924, 2025).
acute myeloid leukemia (1 paper, 2023). Acute myeloid leukemia (AML) is a group of neoplasms arising from precursor cells committed to the myeloid cell-line differentiation. "Acute myeloid leukemia (LAML) expressed lower SLC35A2 than in healthy tissues (P < 0.05)." (PMID 37275857, 2023).
carcinoma in situ (1 paper, 2023). "In another study, Chien-Liang Liu has demonstrated the gradually increased SLC35A2 expression in the cytoplasm from carcinoma in situ to invasive carcinoma, utilizing the immunohistochemical experiments, and this expression pattern also showed the correlation with the stage of BRCA." (PMID 37467193, 2023).
colitis (1 paper, 2022). Inflammation of the colon. "Understanding how these sugars are transported and utilized becomes especially important since various diseases/disorders (LADII, GFUS-CDG, SLC35A2-CDG, PGM1-CDG, colitis, various cancers) are already using or exploring “monosaccharide therapy”." (PMID 36423686, 2022).
colorectal tumors (1 paper, 2025). "Despite immunotherapy has shown promise in treating several cancers in past years, our study revealed that SLC35A2 is highly expressed in microsatellite stable (MSS) colorectal tumors, which is in consistent with unresponsiveness to the immunotherapy." (PMID 40303483, 2025). "Additionally, higher SLC35A2 expression was found in microsatellite stable (MSS) colorectal tumors." (PMID 40303483, 2025).
congenital disorder of glycosylation type IIm (1 paper, 2024). "Mutations in SLC35A2 are listed as the cause of congenital disorder of glycosylation type IIm (CDG2M) or developmental and epileptic encephalopathy-22 (MIM 300896)." (PMID 38649688, 2024). "Mutations in SLC35A2 have previously reported for a developmental and epileptic encephalopathy 22 (DEE22), or congenital disorder of glycosylation type IIm (CDG IIm; MIM 300896)." (PMID 38649688, 2024).
diffuse large B-cell lymphoma (1 paper, 2023). "SLC35A2 was expressed higher in lymphoid neoplasm diffuse large B-cell lymphoma (DLBC), OV, TGCT, and thymoma (THYM) than in the corresponding healthy tissues." (PMID 37275857, 2023).
Focal cortical dysplasia (1 paper, 2025). A type of malformation of cortical development that primarily affects areas of neocortex. "Somatic SLC35A2 variants have also been reported in patients with focal seizures and suspected focal cortical dysplasia." (PMID 41437099, 2025).
head and neck squamous cell carcinoma (1 paper, 2023). A squamous cell carcinoma that arises from any of the following anatomic sites: lip and oral cavity, nasal cavity, paranasal sinuses, pharynx, larynx, and salivary glands. "A significant relationship was revealed between the high level of SLC35A2 methylation and worse OS in head and neck squamous cell carcinoma (HNSC) and kidney renal papillary cell carcinoma (KIRP)." (PMID 37275857, 2023).
Hypsarrhythmia (1 paper, 2025). Hypsarrhythmia is abnormal interictal high amplitude waves and a background of irregular spikes. "Patient harboring SLC35A2 (p.S258F) variant (case #40) exhibited multifocal epileptiform EEG patterns and hypsarrhythmia, reflecting the severe early-onset epileptic phenotypes described in congenital disorders of glycosylation." (PMID 41153369, 2025).
Marfan syndrome (1 paper, 2021). A disorder of the connective tissue. "For the first time, we reported an SLC35A2-CDG patient with concomitant Marfan syndrome (P4)." (PMID 34122512, 2021).
paraganglioma (1 paper, 2023). A benign or malignant neoplasm arising from paraganglia located along the sympathetic or parasympathetic nerves. "Furthermore, increased SLC35A2 expression was noted in uterine carcinosarcoma (UCS), brain lower grade glioma (LGG), adrenocortical carcinoma (ACC), and pheochromocytoma and paraganglioma (PCPG); however, the differences were not statistically significant." (PMID 37275857, 2023).
Saul-Wilson syndrome (1 paper, 2023). "Additionally, de novo variants have been reported in CDG, mainly among ALG13-CDG females, Saul-Wilson syndrome and SLC35A2-CDG." (PMID 37858231, 2023).
stomach cancer (1 paper, 2023). "Nevertheless, these findings may suggest the certain influences of SLC35A2 on the infiltration of immune cells in the immune microenvironment through some potential pathway in gastric cancer, including CD4+ T cell activation and macrophage polarization, which requires further work to confirm." (PMID 37467193, 2023). "Summarily, SLC35A2 may be employed as a reliable prognostic marker for gastric cancer patients, with the potential to serve as an important metabolic regulator in cancer cells and immune cells, which is expected to become a new metabolic and immune target for cancer treatment." (PMID 37467193, 2023).
uveal melanoma (1 paper, 2023). A melanoma derived from melanocytes of the uveal tract. "The results revealed that increased expression of SLC35A2 led to the worse prognosis of nine tumors, including kidney renal clear cell carcinoma (KIRC), LIHC, COAD, PAAD, LGG, KIRP, BRCA, uveal melanoma (UVM), and GBM." (PMID 37275857, 2023).
Ventriculomegaly (1 paper, 2025). An increase in size of the ventricular system of the brain. "We identified a novel SLC35A2-CDG patient carrying a pathogenic variant (c.617_620del, p.(Gln206ArgfsTer45)) who exhibited neurological abnormalities including bilateral ventriculomegaly." (PMID 41008563, 2025).
cancer (15 papers, 2011 to 2025). A tumor composed of atypical neoplastic, often pleomorphic cells that invade other tissues. "SLC35A2 exhibited abnormally high or low expression in 23 cancers and was significantly associated with the prognosis." (PMID 37275857, 2023). "It needs further confirmation in the future to elucidate the underlying mechanism of SLC35A2 in cancer occurrence, progression, metastasis, and immunity." (PMID 37275857, 2023). "Using the DNMIVD tool, we assessed the association between SLC35A2 methylation and cancer patient prognosis." (PMID 37275857, 2023). "The findings revealed a positive association between CNV and SLC35A2 expression in 13 cancers, including BLCA, LUAD, and BRCA (considered significant when FDR ≤ 0.05)." (PMID 37275857, 2023). "The CNV of SLC35A2 showed a positive association with 13 cancer types." (PMID 37275857, 2023). "We evaluated the correlation between SLC35A2 and cancer hallmark pathway scores." (PMID 37275857, 2023). "However, whether SLC35A2 plays an essential role in different cancers via a common underlying molecular mechanism remains unclear." (PMID 37275857, 2023). "High HER2 levels are associated with enhanced activation of the PI3K/AKT and MAPK pathways of cancer, leading to increased proliferation and survival, and it is known that SLC35A2 can also promotes cell metabolism." (PMID 38639872, 2024). "As a result, these findings collectively elucidated the different functions SLC35A2 in oncogenesis and tumor progression in various cancers, with the potential to serve as a predictive biomarker for prognosis of STAD, which deserves further investigation." (PMID 37467193, 2023). "In other words, SLC35A2 is involved in tumor immune evasion and cancer progression by downregulating the number of activated tumor-infiltrating lymphocytes, such as CD8+ T cells, CD4+ T cells, NK cells, and B cells, and ultimately affecting patient survival." (PMID 37275857, 2023). "Based on the UALCAN tool, we identified the promoter hypomethylated status in SLC35A2 in 7 cancer types compared to healthy tissues." (PMID 37275857, 2023). "Exploring the correlation between the expression of immune checkpoint genes and SLC35A2 expression can help understand the prognosis and determine the response to immunotherapy in patients with these cancers." (PMID 37275857, 2023). "The associations between SLC35A2 expression and tumor mutational burden (TMB), microsatellite instability (MSI) in pan-cancer were explored using the SangerBox database." (PMID 37467193, 2023). "Combined with the clinical and pathological features of CRC patients, it was found that SLC35A2 was highly expressed in 78.33% (47/60) of cancer tissue samples, and low expression in 21.67% (13/60) of CRC tissue samples (p < 0.05)." (PMID 37889544, 2023). "SLC35A2 was predominantly related to the mammalian target of rapamycin complex 1 across 33 cancer types." (PMID 37275857, 2023). "In summary, our comprehensive pan-cancer analysis of SLC35A2 helped to characterize SLC35A2 in multiple types of cancers." (PMID 37275857, 2023). "SLC35A2 overexpression predicts a worse prognosis in five types of cancer and is positively correlated with advanced clinical stages in 18 types of cancer." (PMID 37275857, 2023). "We found that SLC35A2 expression negatively correlates with the immune score of seven cancers and the stromal score of nine cancer types." (PMID 37275857, 2023). "In various cancers, SLC35A2 expression and mammalian target of rapamycin complex 1 signaling were positively correlated." (PMID 37275857, 2023). "Our findings confirmed a positive association in SLC35A2 expression with TMB in 14 types of cancer, and MSI in 12 types of cancer." (PMID 37275857, 2023). "The possible downstream pathways of SLC35A2 in different human cancers were explored using gene set variation analysis." (PMID 37275857, 2023).
cancer (continued). "We used the TIMER database to explore the expression of SLC35A2 in pan-cancer and entered the gene name SLC35A2 into the DiffExp module of this website to determine its expression in human tumors and adjacent normal tissues." (PMID 37889544, 2023). "An inverse correlation is observed between SLC35A2 expression and immune score in seven cancer types, including THYM, HNSC, PAAD, PRAD, STAD, LUAD, and COAD (P < 0.05)." (PMID 37275857, 2023). "To determine the gene expression landscape of SLC35A2 in pan-cancer, we integrated different independent datasets from TCGA and GTEx databases." (PMID 37275857, 2023). "SLC35A2 showed significant predictive value for the immunotherapy response of patients with diverse cancers." (PMID 37275857, 2023). "Despite our pan-cancer analysis of SLC35A2 using multi-dimensions, our study still has some limitations that should be addressed." (PMID 37275857, 2023). "To summarize, these findings suggested that SLC35A2 likely plays a critical role in the recruitment and regulation of TILs in cancers." (PMID 37275857, 2023). "Overall, the results above largely support the role of SLC35A2 gene in cancer cell metabolism, which is expected to be a potential new target for regulating cell metabolism to control cancer cell proliferation." (PMID 37467193, 2023). "Since the metastatic ability of cancer cells is closely related to cancer progression 32, we next focused on evaluating whether SLC35A2 affects the migration ability of cancer cells." (PMID 40303483, 2025). "The results revealed that SLC35A2 might influence cancer cell metabolism through downstream molecules related to MYC, including pathways such as steroid biosynthesis, pentose phosphate pathway, and tricarboxylic acid (TCA) cycle." (PMID 40303483, 2025). "The regulation of SLC35A2 in glycosylation also participates in the involvement of cancer process." (PMID 40303483, 2025). "Furthermore, there was a positive correlation between the overexpression of SLC35A2 and reduced lymphocyte infiltration in 13 cancer types, including BRCA and COAD." (PMID 37275857, 2023). "It suggested that SLC35A2 as a significant biological maker involved in various cancer." (PMID 37275857, 2023). "The inconsistent expression of SLC35A2 in pan-cancer may result from the diverse in the methods of data collection in different studies, or the diverse in the underlying biological mechanisms." (PMID 37467193, 2023). "Furthermore, SLC35A2 expression was significantly correlated with pan-cancer immune checkpoints, TMB, MSI, and TIDE genes." (PMID 37275857, 2023). "Therefore, we comprehensively analyzed the expression of SLC35A2 across multiple cancers in multiple datasets." (PMID 37275857, 2023). "It has been reported that the SLC35A2 expression is associated with carcinogenesis in recent studies, however, its specific roles in cancer progression have not been exhaustively elucidated." (PMID 37467193, 2023). "This study highlighted that SLC35A2 may serve as a biomarker for predicting the prognosis of pan-cancer and the response to immunotherapy." (PMID 37275857, 2023). "We found that targeted therapy against SLC35A2 may be helpful for patients with metastatic castration-resistant cancer." (PMID 37275857, 2023). "We subsequently analyzed SLC35A2 genetic alteration in multiple cancers using the cBioPortal tool." (PMID 37275857, 2023). "In summary, SLC35A2 expression was upregulated in various cancers, suggesting that high levels of SLC35A2 may be correlated with tumor progression." (PMID 37275857, 2023). "The upregulated SLC35A2 in five cancer types indicates a poor prognosis." (PMID 37275857, 2023). "Therefore, we performed a pan-cancer analysis of SLC35A2 and found that SLC35A2 is a promising indicator of prognosis and immunotherapy response." (PMID 37275857, 2023). "There is evidence that many cancers affect SLC35A2’s occurrence and development as a NST member." (PMID 37889544, 2023).